CLCN3 (Cl-/H+ antiporter 3)
Diseases named in the same sentence as CLCN3 in open-access papers (continued):
Sharing a sentence is not in itself a finding about the gene and the disease.
cancer (31 papers, 2013 to 2025). A tumor composed of atypical neoplastic, often pleomorphic cells that invade other tissues. "The ClC-3 chloride channel/antiporter, encoded by the Clcn3, is associated with some diseases, like carcinoma, nervous system diseases, and metabolic diseases." (PMID 38784133, 2024). "Our findings in this study indicate that CLCN3 promotes 3D spheroid proliferation in ErbB2-overexpressing breast epithelial and cancer cells." (PMID 31608175, 2019). "CLCN3 was decreased in cancer compared to control by 0.80-fold, p = 0.09 (RT-PCR) vs. 0.84-fold, p = 0.01 (microarray)." (PMID 25705890, 2015). "CLCN3, which encodes chloride voltage‐gated channel 3 (CIC‐3), has been implicated in cell proliferation, migration, and chemotherapy resistance in several cancers." (PMID 40145859, 2025). "By isolating primary cancer-associated fibroblasts (CAFs) from human LUAD, we confirmed that decreased extracellular CLCN3 secretion induced by HNRNPK knockdown inhibited CAFs activation and TGF-β1 production, thus suppressing nuclear HNRNPK expression and LUAD progression in a feedback way." (PMID 36439880, 2022). "In addition, CLCN3 promotes 3D spheroid proliferation in ErbB2-overexpressing breast epithelial and cancer cells." (PMID 31608175, 2019). "In addition, several studies have shown that CLCN3 is involved in cell proliferation, apoptosis, drug resistance, and invasion in many cancers." (PMID 31608175, 2019). "Thus, there are several reports on the functions of CLCN3 in cancer." (PMID 31608175, 2019). "Therefore, CLCN3 may function critically in the initiation and development of cancer." (PMID 36439880, 2022).
tumor (22 papers, 2013 to 2025). "Taken together with the ex vivo analyses, these experiments underscore the tight reciprocal association between the expression of miRNA-1a-3p and Clcn3 and established their in vivo validity as a miRNA–mRNA modulatory pair in DRGs of tumour-bearing mice." (PMID 24039159, 2013). "Thus downregulating expression of Clcn3 in the DRG exerted the same functional effect on tumour-associated mechanical hypersensitivity as inhibition of miR-1a-3p, again emphasizing the in vivo significance of miR-1a-3p-Clnc3 as a miRNA–mRNA regulatory pair." (PMID 24039159, 2013). "Interestingly, a knockdown of Clcn3 expression in DRG was associated with exaggerated mechanical hypersensitivity to plantar application of von Frey stimuli in tumour-bearing mice." (PMID 24039159, 2013). "In silico analyses revealed that their predicted targets include key pain-related genes and we identified Clcn3, a gene encoding a chloride channel, as a key miRNA target in sensory neurons, which is functionally important in tumour-induced nociceptive hypersensitivity in vivo." (PMID 24039159, 2013). "We discovered that a correlation existed between higher HNRNPK expression and deeper tumor invasion (P = 0.019), and a correlation between greater CLCN3 expression and an elevated probability of lymph node metastases (P = 0.027)." (PMID 36439880, 2022). "Subsequently, to observe the functional regulation of CLCN3 on tumor metastasis in vivo, stable HNRNPK-knockdown cells (H1299) and rescue model cells were transfected with luciferase plasmids and then injected into nude mice's tail veins." (PMID 36439880, 2022). "This study suggested that HNRNPK/CLCN3 axis facilitated the LUAD progression through tumor cell interactions with CAFs." (PMID 36439880, 2022). "Specific Clcn3 knock-down in DRG neurons confirmed its crucial role in tumor-induced mechanical hypersensitivity." (PMID 28887457, 2017). "To confirm the change in Clcn3 mRNA expression in the DRGs of tumour-bearing mice, we performed a qRT-PCR-based analysis of the time-course of regulation at different time points after tumour cell implantation as compared with sham controls at each time point." (PMID 24039159, 2013). "HNRNPK/CLCN3 axis facilitates the progression of LUAD through CAF-tumor interaction." (PMID 36439880, 2022). "Furthermore, this phenomenon was rescued and reversed after the addition of TGF-β1, which validated that the CLCN3-TGFβ1-HNRNPK axis facilitated LUAD progression through interaction between tumor cells and CAFs." (PMID 36439880, 2022). "Overall, our findings suggest that the HNRNPK/CLCN3 axis might act as an important mediator of CAF-tumor interaction in LUAD progression." (PMID 36439880, 2022). "Thus, CLCN3 facilitated tumor proliferation and migration, exerting an oncogenic role in human LUAD." (PMID 36439880, 2022). "Finally, we tested the functional significance of knocking down Clcn3 expression in DRG in the context of tumour-induced hypersensitivity." (PMID 24039159, 2013). "Furthermore, the phenotype of exaggerated tumour-mediated hyperalgesia evoked by specifically knocking Clcn3 expression down in sensory neurons in vivo matched perfectly with attenuation of tumour-mediated hyperalgesia evoked by miR-1a-3p knockdown in the DRG." (PMID 24039159, 2013). "Thus, we further examined the role of CLCN3 in tumor proliferation and migration in vitro." (PMID 36439880, 2022). "In addition, IHC staining of CLCN3 and HNRNPK in tumor xenografts revealed that the expression of CLCN3 was decreased after HNRNPK silencing but that this reduction could be restored by CLCN3 upregulation." (PMID 36439880, 2022). "However, the magnitude of increase in the mechanical sensitivity upon Clcn3 knock-down in naïve mice was lesser in magnitude than when compared to magnitude of the effect of Clcn3-siRNA on tumour-mediated hyperalgesia, consistent with a regulation of Clcn3 expression in tumour states." (PMID 24039159, 2013).
tumor (continued). "Fifty‐one candidate proteins were identified, and we selected three top‐ranked, tumor‐related candidates (STK33, CLCN3, and RhoA) from the top 15 ranked proteins for further validation using SPR assays." (PMID 40908551, 2025). "We observed that the tumor weight and growth were significantly suppressed following HNRNPK knockdown, and the inhibitory influence was abrogated by CLCN3 overexpression." (PMID 36439880, 2022). "In summary, anti-inflammatory CLCN3 signaling and high levels of Parabacteroides merdae combined with anti-oncogenic TGF-β/CLIC4 signaling exhibited an anti-tumor effect." (PMID 28445967, 2017). "Firstly, CLCN3 was upregulated in human LUAD and facilitated tumor proliferation and migration." (PMID 36439880, 2022). "Finally, the expression and function of CLCN3 were regulated by HNRNPK in vitro and in vivo, and the HNRNPK-CLCN3 axis facilitated LUAD progression in a feedback way through CAF-tumor interaction in the TME." (PMID 36439880, 2022). "The key biological activities of CLCN3, which were reduced following HNRNPK downregulation and elevated following HNRNPK upregulation in vitro, demonstrate that HNRNPK performs a role in the promotion of tumor growth." (PMID 36439880, 2022). "Therefore, our data support that the HNRNPK/CLCN3 axis facilitated LUAD progression through the interaction between CAFs and tumor cells." (PMID 36439880, 2022). "We observed that Clcn3 is significantly and consistently downregulated starting from PID-4 until PID-15, which is in complete agreement with the time-course of development of tumour-induced mechanical hyperalgesia." (PMID 24039159, 2013). "To investigate whether Clcn3 is also involved in the modulation of basal mechanical sensitivity, we performed Clcn3 knockdown in L3-L4 DRGs of wild-type mice in the absence of tumour induction." (PMID 24039159, 2013).
nervous system diseases (3 papers, 2019 to 2025). "Since activating mutations in CLCN3 and CLCN4 are associated with neurological disease, we expect to find T9 CID mutations in nervous system disorders." (PMID 40169677, 2025).
metabolic disease (2 papers, 2016 to 2024). A congenital disorder (due to inherited enzyme abnormality) or acquired (due to failure of a metabolically important organ) disorder resulting from an abnormal metabolic process. "Clcn3 will be a target in the treatment of metabolic diseases." (PMID 38784133, 2024).
neurodevelopmental disorder (2 papers, 2023 to 2025). A behavioral and cognitive disorder with onset during the developmental period that involves impaired or aberrant development of intellectual, motor, or social functions. "Variants in CLCN3 and CLCN4, encoding the neuronal endosomal Cl−/H+ antiporters ClC-3 and ClC-4, are linked to neurodevelopmental disorders with broad phenotypic variability." (PMID 41439993, 2025). "De novo heterozygous missense variants in CLCN3 were identified in 9 unrelated patients who had neurodevelopmental disorders with hypotonia and brain abnormalities." (PMID 38025430, 2023). "Variants in both CLCN3 and CLCN4 are associated with neurodevelopmental disorders that share partially overlapping but distinct symptom profiles." (PMID 41439993, 2025).
CLCN3 also shares sentences with these, for which no sentence is quoted: nasopharyngeal carcinoma (8 papers); prostate carcinoma (7); gastric cancer (6); cervical carcinoma (5); endometriosis (3); heart failure (3); Hypertension (3); inflammatory bowel disease (3); colitis (2); colorectal cancer (2); Dent disease (2); diabetes (2); gastric adenocarcinoma (2); hepatocellular carcinoma (2); Intellectual disability (2); leukemia (2); lung carcinoma (2); lymph node metastasis (2); type 2 diabetes mellitus (2); Alazami syndrome (1); allergic asthma (1); Alzheimer disease (1); Anxiety (1); asthma (1); autism (1); Blindness (1); brain tumours (1); breast adenocarcinoma (1); breast tumors (1); cardiovascular disease (1).
A further 33 diseases each share a sentence with CLCN3 in 1 paper.